ALOX12B (arachidonate 12-lipoxygenase, 12R type)
Description:
Catalyzes the regio and stereo-specific incorporation of a single molecule of dioxygen into free and esterified polyunsaturated fatty acids generating lipid hydroperoxides that can be further reduced to the corresponding hydroxy species. In the skin, acts upstream of ALOXE3 on the lineolate moiety of esterified omega-hydroxyacyl-sphingosine (EOS) ceramides to produce an epoxy-ketone derivative, a crucial step in the conjugation of omega-hydroxyceramide to membrane proteins. Therefore plays a crucial role in the synthesis of corneocytes lipid envelope and the establishment of the skin barrier to water loss. May also play a role in the regulation of the expression of airway mucins.
Synonyms: 12R-LOX; ARCI2
Tractability: Small molecule: it belongs to a druggable protein family.
Gene: Protein-coding gene on chromosome 17 (8,072,636 to 8,087,716, reverse strand). Ensembl gene ENSG00000179477.
Subcellular location: Cytoplasm; Cytoplasm, perinuclear region
Subcellular location (Human Protein Atlas): Cytosol; Vesicles
Pathways (Reactome):
Metabolism: Synthesis of 12-eicosatetraenoic acid derivatives
Gene Ontology:
Molecular function: arachidonate 12(R)-lipoxygenase activity; arachidonate 12(S)-lipoxygenase activity; oxidoreductase activity, acting on single donors with incorporation of molecular oxygen, incorporation of two atoms of oxygen; linoleate 9S-lipoxygenase activity; arachidonate 8(R)-lipoxygenase activity; iron ion binding; metal ion binding
Biological process: arachidonate metabolic process; lipoxygenase pathway; positive regulation of gene expression; positive regulation of MAPK cascade; positive regulation of mucus secretion; sphingolipid metabolic process; ceramide biosynthetic process; establishment of skin barrier; hepoxilin biosynthetic process; linoleic acid metabolic process; protein lipidation; lipid oxidation
Cellular component: cytosol; perinuclear region of cytoplasm; cytoplasm
Genetic constraint (gnomAD): Loss-of-function variants: 50 observed, 80.78 expected, observed/expected ratio (o/e) 0.62, 90% interval 0.49 to 0.78. The upper end of that interval is the gene's LOEUF score, 0.78, which puts it in group 3 of 6, group 1 being the genes least tolerant of losing a copy. Missense variants: 805 observed, 954.52 expected, observed/expected ratio (o/e) 0.84, 90% interval 0.8 to 0.89. Synonymous variants: 370 observed, 387.83 expected, observed/expected ratio (o/e) 0.95, 90% interval 0.88 to 1.04.
Homologues: Orthologues: chimpanzee ALOX12B (99% identical), macaque ALOX12B (98% identical), pig ALOX12B (90% identical), dog ALOX12B (88% identical), rat Alox12b (87% identical), mouse Alox12b (86% identical), guinea pig ALOX12B (86% identical), rabbit ALOX12B (80% identical). Paralogues in human: ALOXE3 (53% identical), ALOX15B (48% identical), ALOX5 (39% identical), ALOX12 (36% identical), ALOX15 (33% identical).
Diseases named in the same sentence as ALOX12B in open-access papers:
ALOX12B is named in the same sentence as 54 diseases in open-access papers, as found by Europe PMC text mining. Sharing a sentence is not in itself a finding about the gene and the disease. The quoted sentences say what the papers report.
ichthyosis (21 papers, 2012 to 2026). Disorders of cornification that are characterized by visible scaling and/or hyperkeratosis of most or all of the skin. "ALOX12B and ALOXE3 play important roles in skin development and mutations in the ALOX12B gene have been related to ichthyosis, a genetic skin disease characterized by dry, thickened, and scaly skin." (PMID 40683369, 2025). "Mutations in ALOX12B resulted in impaired keratinization, thus causing autosomal recessive congenital ichthyosis." (PMID 41380997, 2025). "Here, the authors report the case of a 2 years and 6 months-old boy with congenital ichthyosis induced by genetic mutations in ALOX12B, who underwent dental treatment under general anesthesia." (PMID 39917683, 2024). "The mutation in the ALOX12B gene is linked with the development of autosomal recessive congenital ichthyosis, confirming the importance of 12(R)-LOX for the maintenance of the skin permeability barrier." (PMID 36837912, 2023). "12R-LOX is important in skin function; mutations in the ALOX12B gene lead to ichthyosis, as do mutations in the ALOXE3 gene." (PMID 36765904, 2023). "A genetic analysis of patients with ichthyosis over a period of 26 years revealed 170 families with mutations in ALOX12B or ALOXE3 in our laboratories; a further 54 families were contributed by other coauthors within the ERN-Skin network." (PMID 33435499, 2021). "Both epidermis-specific Mll4-knockout mice and Alox12b loss-of-function mutant mice exhibited epidermal hyperproliferation, scaling, and other cutaneous manifestations similar to ichthyosis, as well as a deficiency of ALOX12b expression in the epidermis of both mice." (PMID 36684424, 2022). "Exome sequencing followed by segregation analysis identified pathogenic variants in four established ichthyosis-associated genes: CYP4F22, FLG, ALOX12B, and NIPAL4." (PMID 42196615, 2026). "While ALOX12B-ARCI shares surface phenotypic features with syndromic ichthyoses, such as Netherton syndrome or STAT3 HIES, its immunological footprint appears milder, incomplete, and most consistent with secondary immune dysregulation." (PMID 41346588, 2025). "Large droplets such as those seen in CRISPR-LOX TESs were also observed in skin samples from patients with a mutated form of ALOX12B in ARCI cases and in other forms of ichthyosis, as well as in Alox12b knockout mice; however, their nature remained unclear." (PMID 40981344, 2025). "This is supported by the observation of skin pathological changes in mouse models with knockouts of MLL4 and ALOX12B genes, which exhibit features similar to ichthyosis." (PMID 39430757, 2024). "Mutations in the LOX gene family, specifically arachidonic acid 12-lipoxygenase (ALOX12B) and arachidonate lipoxygenase 3 (ALOXE3), are common causes of ichthyosis." (PMID 39430757, 2024). "The identification of genes associated with ichthyosis, such as MLL4 and ALOX12B, has opened up new avenues for understanding the molecular mechanisms underlying the disease." (PMID 39430757, 2024). "In mouse models with specific knockouts of the MLL4 and ALOX12B genes, skin pathological changes similar to ichthyosis, including epidermal hyperplasia and desquamation, were observed." (PMID 39430757, 2024). "The skin pathological changes observed in mouse models with knockouts of the MLL4 and ALOX12B genes, which resemble ichthyosis, provide experimental evidence supporting the treatment of ichthyosis through targeting the ferroptosis pathway." (PMID 39430757, 2024). "We found that NEAT1 is upregulated in Ichthyosis lamellar human samples and in Alox12B KO mice, a mouse model resembling this skin disease." (PMID 37365156, 2023). "To date, multiple genes have been shown to be associated with ichthyosis, including ALOXE3, ALOX12B, TGM1, CYP4F22, NIPAL4, and ABCA12." (PMID 24278723, 2012).
ichthyosis (continued). "Mice with functional loss mutations in the ALOX12B gene induced by ethylnitrosourea had red and shiny skin at birth, but quickly became dry and led to death, without exhibiting typical ichthyosis-like lesions." (PMID 39430757, 2024). "Using whole-exome sequencing (WES), we identified the first case of ichthyosis due to a maternal mixUPD on chromosome 17, which results in a homozygous deletion of partial intron 8 to exon 10 in ALOX12B, being predicted to lead to an internal protein deletion of 97 amino acids." (PMID 36003334, 2022). "There are 6 genes currently known to be associated with ichthyosis: ALOXE3, ALOX12B, TGM1, CYP4F22, NIPAL4, and ABCA12, and although thought to be unrelated, both the probands from family 1 and family 2 harboured an identical novel missense variant, c.G4676T, p.Gly1559Val in ABCA12." (PMID 24278723, 2012). "Additionally, modulating MLL4 and ALOX12B may prove to be an effective approach to treating ichthyosis." (PMID 39430757, 2024). "Additionally, 15 genes involved in lipid metabolism were differentially expressed, some directly involved in ichthyosis, e.g., ABCA12, ALOX5, ALOX12B, ALOXE3, CYP4F2, and 2 elongation of very long chain fatty acid protein (ELOV) genes." (PMID 32544098, 2020).
autosomal recessive congenital ichthyosis (16 papers, 2012 to 2025). Autosomal recessive form of inherited ichthyosis. "Based on clinical examination and genetic testing, a diagnosis of SICB was confirmed, with mutations identified in genes commonly associated with autosomal recessive congenital ichthyosis, such as ALOX12B, TGM1, ALOXE3, CYP4F22, and PNPLA1." (PMID 40193669, 2025). "Eight patients were affected by autosomal recessive congenital ichthyosis associated with ALOX12B, NIPAL4, and TGM1 mutations." (PMID 38791074, 2024). "Genetic evidence has linked missense and splice site mutations in ALOXE3 and ALOX12B to the incidence of autosomal recessive congenital ichthyosis (ARCI)—a severe disorder of keratinization." (PMID 38612771, 2024). "Pathogenic variants in ALOX12B, a crucial enzyme involved in epidermal lipid processing, are among the most common causes of autosomal recessive congenital ichthyosis (ARCI)." (PMID 41346588, 2025). "Autosomal recessive congenital ichthyosis (ARCI) is associated with mutations in at least 10 genes, such as TGM1, ALOXE3, ALOX12B, ABCA12, and others." (PMID 40565081, 2025). "Our study reports the first case of autosomal recessive congenital ichthyosis (ARCI) due to a mixUPD of chromosome 17 and expands the spectrum of clinical manifestations of ARCI caused by mutations in the ALOX12B gene." (PMID 36003334, 2022). "It has been established that ALOX12, ALOX12B, and ALOXE3 mutations can cause autosomal recessive congenital ichthyosis (ARCI)." (PMID 36684424, 2022).
cervical cancer (7 papers, 2021 to 2024). A primary or metastatic malignant neoplasm involving the cervix. "ALOX12B has been reported to promote the carcinogenesis of cervical cancer and is associated with an increased risk of breast cancer." (PMID 36142451, 2022). "However, another study revealed that ALOX12B mediates cervical cancer cell proliferation and migration via the PI3K-ERK1 pathway." (PMID 35768785, 2022). "In current study, we identified a reliable metabolism-related signature composed of ALOX12B, CA9, FAR2, F5 and TDO2 for the prognosis and anti-tumor immunity in cervical cancer." (PMID 35626004, 2022). "Among the five genes, the expression of ALOX12B and F5 was decreased, while that of CA9, FAR2 and TDO2 was relatively elevated in cervical cancer samples, as indicated by the IHC results." (PMID 35626004, 2022). "Among them, ALOX12B and CDO1 were not expressed in both normal cervical and cervical cancer tissues." (PMID 36313765, 2022).
Non-bullous Congenital Ichthyosiform Erythroderma (3 papers, 2022 to 2025). "The involvement in the CLE assembly of eLOX-3 and 12R-LOX (enzymes, respectively, encoded by the ALOXE3 and ALOX12B genes) was considered because mutations within these genes are associated with the Non-bullous Congenital Ichthyosiform Erythroderma (NCIE)." (PMID 40981344, 2025). "The authors performed whole-exome sequencing in his peripheral blood and found that the patient had compound heterozygous mutations in ALOX12B gene (c.159C>G and c.1579G>A), which is responsible for autosomal recessive congenital ichthyosis-2 (MIM#2421000)." (PMID 39917683, 2024). "Generally, mutations in ALOX12B are not severe but cause congenital ichthyosiform erythroderma and a kink in the ear helix." (PMID 39917683, 2024).
psoriasis (3 papers, 2016 to 2024). An autoimmune condition characterized by red, well-delineated plaques with silvery scales that are usually on the extensor surfaces and scalp. "Our analysis revealed the upregulation of 3 ferroptosis markers (Chac1, Slc40a1, Fth1) and 29 ferroptosis drivers (including Alox12B and Alox15B, which encodes 15-LOX-2) as well as downregulation of 7 ferroptosis suppressors in psoriasis." (PMID 39570671, 2024). "Mutation of ALOX12B and/or SPRR1A may result in skin barrier-related diseases, such as psoriasis and autosomal-recessive exfoliative ichthyosis." (PMID 35768785, 2022).
breast carcinoma (2 papers, 2022). "As expected, several of the genes associated with top differentially methylated probes between these groups have been previously implicated in breast cancer, including SDC2, PBK, ALOX12B, DAG1, ZNF382, and FST." (PMID 35564499, 2022).
Erythema (2 papers, 2015 to 2022). Redness of the skin, caused by hyperemia of the capillaries in the lower layers of the skin. "It has been previously reported that a 35-year-old male with homozygous deletion of ALOX12B exon 3–15 had a mild body erythema in his childhood and only very mild face erythema with palmar hyperlinearity in adulthood." (PMID 36003334, 2022).
Hyperkeratosis (2 papers, 2015 to 2021). Hyperkeratosis is a histopathological term defining a thickened stratum corneum and may be present in many different skin conditions, with many possible overlaps. "However, upregulated FLG reflects hyperkeratosis, while ALOX12B, ALOXE3, and KRT16 are wound-activated genes in the oral mucosa, suggesting an ongoing wound repair process." (PMID 34506598, 2021).
keratoderma (2 papers, 2016). "ALOX12B and CYP4F22 mutations usually produce moderate keratoderma." (PMID 26762237, 2016).
sarcoma (2 papers, 2019 to 2022). A usually aggressive malignant neoplasm of the soft tissue or bone. "Except for ALOX12B, the 17p copy number gains of MSK-IMPACT-assessed genes were associated with increased gene expression in the sarcoma TCGA analysis." (PMID 35705560, 2022).
Alzheimer disease (1 paper, 2014). A progressive, neurodegenerative disease characterized by loss of function and death of nerve cells in several areas of the brain leading to loss of cognitive function such as memory and language. "mRNA and protein levels of cPLA2 IVA (PLA2G4A), sPLA2 IIA (PLA2G2A), COX-1 and -2 (PTGS1, PTGS2), mPGES1 (PTGES1), and LOX-12 and -15 (ALOX12B, ALOX15B), are increased in Alzheimer's disease in the frontal cortex, hippocampus, and cerebellum." (PMID 24963629, 2014).
atopic dermatitis (1 paper, 2019). "We assumed that the increase of trihydroxy-linoleic acids in atopic dermatitis patients is due to the increased gene expression of enzymes involved in CLE formation, ALOX12B (12R-LOX), ALOXE3 (eLOX3), and ABHD9 (EPHX3)." (PMID 30608955, 2019).
colon cancer (1 paper, 2025). "In the colon cancer cell lines HCT116 and SW480 treated with solanine, the expression of arachidonate 12-lipoxygenase B (ALOX12B) and arachidonate 5-lipoxygenase (ALOX5) was significantly upregulated in a dose-dependent manner." (PMID 41471274, 2025). "Silencing adenylate cyclase 4 (ADCY4) could reduce the stability of ALOX12B and inhibit its overexpression, which indicates that ADCY4 is crucial for maintaining the expression and stability of ALOX12B, essential for the effective execution of ferroptosis in colon cancer cells treated with solanine." (PMID 41471274, 2025).
colorectal tumor (1 paper, 2022). "They showed that the expression level of ALOXE3, ALOX5, ALOX12, and ALOX12B was upregulated in colorectal tumor samples." (PMID 35928873, 2022).
congenital hydronephrosis (1 paper, 2022). Congenital hydronephrosis is a renal urinary disease characterized by distension and dilation of the renal pelvis and calyces secondary to various congenital obstructive malformations of the kidneys and urinary tract that can evolve to renal atrophy. "The patient with the c.526G>A mutation in the ALOX12B gene, in addition to fractures, had keratinization of the skin and congenital hydronephrosis." (PMID 35052464, 2022).
cryptorchidism (1 paper, 2022). The failure of one or both testes of a male fetus to descend from the abdomen into the scrotum during the late part of pregnancy. "Furthermore, in this case, the proband presented with cryptorchidism, which has not been reported yet to be associated with the ALOX12B gene." (PMID 36003334, 2022).
epidermoid carcinoma (1 paper, 2021). "ALOX12B encodes lipoxygenase, which is associated with autosomal dominant fish scale disease and proliferation of epidermoid carcinoma cells." (PMID 34804126, 2021).
epilepsy (1 paper, 2024). A brain disorder characterized by episodes of abnormally increased neuronal discharge resulting in transient episodes of sensory or motor neurological dysfunction, or psychic dysfunction. "Four diagnostic biomarkers (ALOX12B, CBS, CPT1C, and DAGLB) showed high accuracy for epilepsy diagnosis, with an AUC value of 0.9592." (PMID 38419709, 2024). "Our research unveiled potential DELMRGs (ALOX12B, CBS, CPT1C and DAGLB) in TSE, which may provide new ideas for studying the psathogenesis of epilepsy." (PMID 38419709, 2024). "Our research identified potential DELMRGs (ALOX12B, CBS, CPT1C, and DAGLB) in epilepsy, which may provide new ideas for studying the pathogenesis of Epilepsy." (PMID 38419709, 2024).
glioblastoma (1 paper, 2022). The most malignant astrocytic tumor (WHO grade IV). "ALOXE3 as a paralog of ALOX12B, inhibits glioblastoma tumor migration." (PMID 35768785, 2022).
head and neck squamous cell carcinoma (1 paper, 2023). A squamous cell carcinoma that arises from any of the following anatomic sites: lip and oral cavity, nasal cavity, paranasal sinuses, pharynx, larynx, and salivary glands. "Downregulation of ALOX12B prompts poor survival rate and advanced stages negative HPV 16-negative head and neck squamous cell carcinoma." (PMID 37221577, 2023).
lung carcinoma (1 paper, 2023). "Further, through thousands of protein screenings, we identified four proteins (MYH9, GNB1, ALOX12B, HSD17B4) that can predict the response to MET inhibitors for MET-dysregulated lung cancer patients." (PMID 36612298, 2023).
ovarian tumor (1 paper, 2018). "The unbiased approach showed that expression of ALOX5 and ALOX12B are significantly higher in “high” expressing group, compared to the “low” expressing group, in the TCGA ovarian tumor cohort (n = 216; ALOX5 p = 0.00108 and ALOX12B p = 0.00248) as well as in other tumor cohorts." (PMID 30258081, 2018).
periodontitis (1 paper, 2024). An acute or chronic inflammatory process that affects the tissues that surround and support the teeth. "The results derived from the three machine learning methods were intersected and illustrated in a Venn diagram, revealing six transcriptional biomarkers critical for differentiating periodontitis tissues from healthy tissues: ALOX12B, BNIP3, CEBPG, LURAP1L, RGS4, and TFAP2C." (PMID 39045324, 2024). "Secondly, our study identified six transcripts that are tissue biomarkers for periodontitis (ALOX12B, BNIP3, CEBPG, LURAP1L, RGS4, and TFAP2C) potentially significant for periodontitis using three machine learning methods: LASSO, SVM, and RF." (PMID 39045324, 2024). "LURAP1L and RGS4 showed significant overexpression, whereas ALOX12B, BNIP3, CEBPG, and TFAP2C were notably underexpressed in periodontitis." (PMID 39045324, 2024).
type 2 diabetes mellitus (1 paper, 2020). A type of diabetes mellitus that is characterized by insulin resistance or desensitization and increased blood glucose levels. "Another study checked the association between genetic variants of ALOX5, ALOX12, ALOX12B, and ALOX15, and type-2 diabetes mellitus (T2D), and found that ALOX12 and ALOX12B genetic variants increased susceptibility to T2D development, possibly though alterations in PUFA/ARA metabolism." (PMID 32235564, 2020).
xerosis (1 paper, 2024). "It was found in trans with a known pathogenic large deletion removing exons 3–15 of ALOX12B, in a child (case ID.04) with congenital dyskeratosis, pigmented areas of cutaneous xerosis located in the axillary region, on the sides and the legs bilaterally, and very mild face erythroderma." (PMID 38791074, 2024).